PFKFB4 (6-phosphofructo-2-kinase/fructose-2,6-biphosphatase 4)
Diseases named in the same sentence as PFKFB4 in open-access papers (continued):
Sharing a sentence is not in itself a finding about the gene and the disease.
cancer (continued). "Furthermore, CBD decreased the expression of genes responsible for glucose metabolism, glycolysis, and gluconeogenesis, such as PFKFB4, which regulates fructose-2,6-bisphosphate and responds to hypoxia to help cancer cells produce more ATP." (PMID 37834191, 2023). "Moreover, PFKFB4 is induced by hypoxia, is required for survival and proliferation of normal thymocytes as well as of several cancer cell lines such as lung, breast, and colon adenocarcinomas and prostate and bladder cancer." (PMID 35914811, 2022). "Understanding the role of PFKFB4 in tumor cell survival could allow it to be leveraged in a cancer therapy." (PMID 36115843, 2022). "Moreover, we found PFKFB4 gene expression showed a strong correlation with genes involved in glycolytic pathway in all cancers studied." (PMID 35902861, 2022). "Both PFKFB3 and PFKFB4 have been shown to be overexpressed in cancer." (PMID 36115843, 2022). "Nevertheless PFKFB4-mediated glycolysis contributes to the autophagy regulation in cancer." (PMID 36034839, 2022). "PFKFB3 and PFKFB4 affect carcinogenesis and cancer metabolism in a multidirectional manner." (PMID 33671514, 2021). "Of note, PFKFB4 expression in ccRCC was among the top 10 highest amid all TCGA cancers." (PMID 34593007, 2021). "Previous studies identified that reduced lactate secretion and intracellular ATP levels were observed in malignant cells when PFKFB4 was silenced, and the induction of lipid synthesis, which is required for cancer cell growth, was inhibited, possibly by reducing NADPH availability." (PMID 34211613, 2021). "Thus, PFKFB4 participating in core metabolic pathways have proven to be essential for the proliferation and survival of cancer cells." (PMID 34593007, 2021). "Reports on the importance of PFKFB3 and PFKFB4 in cancer development and progression strongly suggest that these isozymes may represent promising targets for new potent personalized therapies in cancer treatment." (PMID 33671514, 2021). "Recent discoveries related to PFK-2 isozymes, especially PFKFB3 and PFKFB4, in cancer progression and development, have identified their inhibitors as potent therapeutic agents that could play an important role in future cancer treatment." (PMID 33671514, 2021). "Interestingly, the only gene, which expression was strongly altered in hypoxic (1% O2) conditions was PFKFB4, the one coding for the cancer-specific isoenzyme of phosphofructokinase II (PFK-II)." (PMID 34445551, 2021). "PFKFB3 and PFKFB4 are the two primary isoenzymes overexpressed in various kinds of human cancers." (PMID 34211613, 2021). "However, most recent studies have focused on an increased expression of PFKFB3 and PFKFB4 in cancer tissues and their role in carcinogenesis." (PMID 33671514, 2021). "PFKFB4 was reported to exert dual function in other cancers." (PMID 34593007, 2021). "Cancer cells utilize enzymes with recently discovered functions, such as PFKFB4, that introduces phosphate groups to proteins, which may contribute to the tumorigenesis of various solid cancers." (PMID 31139559, 2019). "Recent studies reported PFKFB4 as a potential target in cancer." (PMID 31244553, 2019). "PFKFB4 expression is also controlled by heme-oxygenase-2 in HepG2 cancer cells." (PMID 30234009, 2018). "Moreover, it has been demonstrated that PFKFB4 mRNA and protein levels are regulated by hypoxia and glucose levels in different cancer cell lines from the prostate, liver, colon, bladder, stomach and pancreas." (PMID 30234009, 2018). "Thus PFKFB4 seems to be essential to keep balance between glycolytic activity and antioxidant production at least in cancer cells." (PMID 27187453, 2016). "Recent studies have demonstrated that cancer cells from several tissue origins and genetic backgrounds require the expression of 6-phosphofructo-2-kinase/fructose-2,6-bisphosphatase 4 (PFKFB4), a regulatory enzyme that synthesizes an allosteric activator of glycolysis, fructose-2,6-bisphosphate." (PMID 26221874, 2015).
cancer (continued). "The observation that pharmacological inhibition of the kinase domain of PFKFB4 suppresses cell proliferation thus provides “proof-of-concept” that PFKFB4 kinase, as opposed to bisphosphatase inhibitors, may have utility as anti-cancer agents." (PMID 26221874, 2015). "Furthermore, we find that the cell cycle arrest effects of 5MPN can be overcome by over-expression of PFKFB4 indicating that the anti-cancer effects of 5MPN are due, at least in part, to its inhibition of PFKFB4." (PMID 26221874, 2015). "In 2012, two independent groups reported the results of unbiased screens for genes essential for cancer survival; they found that PFKFB4 expression was essential for the survival of glioma stem-like cells and prostate cancer cells but not for normal cell survival." (PMID 26221874, 2015). "Based on these studies, we anticipated that pharmacological disruption of the kinase domain of PFKFB4 may decrease the glucose metabolism and growth of human cancers." (PMID 26221874, 2015). "However, PFKFB4 was subsequently observed to be expressed in multiple organs and to be over-expressed in human tumors indicating a potential role in cancer development and/or progression." (PMID 26221874, 2015). "Although PFKFB4 appears to be a rational target for anti-neoplastic drug development, it is not clear whether its kinase or phosphatase activity is required for cancer cell survival." (PMID 25115398, 2014). "We predict that pharmacological disruption of the PFKFB4 kinase domain may have clinical utility for the treatment of human cancers." (PMID 25115398, 2014). "An essential first step in developing anti-cancer agents that inhibit PFKFB4 is to determine whether the kinase or phosphatase domain of this bifunctional enzyme are active in neoplastic cells." (PMID 25115398, 2014). "Moreover, the qPCR and IHC results indicated that the knockdown of PFKFB4 could decrease the cancer stemness and EMT capability, which was evidenced by reduced levels of stemness and EMT‐related markers." (PMID 36127291, 2023). "Interestingly, while PFKFB4 had a widespread copy-number loss in glycolytic cancer types, its transcript expression was markedly higher in glycolytic cancers compared to non-glycolytic cancers." (PMID 36831501, 2023). "Thus, the therapeutic implications of targeting PFKFB3 and PFKFB4 could disrupt glycolysis or Warburg effect and eliminate other signaling mechanisms for cancer progression." (PMID 37919747, 2023). "Several studies revealed that targeting PFKFB3 and PFKFB4 could inhibit glycolysis in cancer cells." (PMID 37919747, 2023). "Interestingly, PFKFB4 may even regulate the infiltration of immune cells in tumor tissues, which suggests that PFKFB4 may also be a promising target for the regulation of tumor immunity in some types of cancer." (PMID 35902861, 2022). "The disruption of this interaction could be an additional strategy to block PFKFB4 in cancer." (PMID 35914811, 2022). "Consistently, we found that several downregulated genes associated with cancer cells metabolism (Pfkfb3, Fgfbp1, Gnas, Pfkfb4, Ctnnb1, and Tsta3) in the colon of EgPSC-infected mice, indicating that intraperitoneally EgPSC infection may elicit protective effect in cancer development." (PMID 36713407, 2022). "In order to investigate whether the PFKFB4 gene is also involved in the cytokine-mediated inflammatory microenvironment and subsequent metastasis process in tumor tissues, we evaluated the correlation of PFKFB4 expression and tumor pathological stages in several types of cancer." (PMID 35902861, 2022). "Hence, these studies demonstrated that PFKFB4 might be a useful molecular marker and potential target for the development of cancer therapeutics." (PMID 34211613, 2021).
cancer (continued). "The Warburg pathway enzyme 6-phosphofructo-2-kinase/fructose-2,6-bisphosphatase 4 (PFKFB4) is implicated in regulation of diverse biological processes and plays an important role in regulating glucose metabolism and guiding macromolecule biosynthesis to promote proliferation of cancer cells." (PMID 34556750, 2021). "Furthermore, we highlight crucial studies on targeting PFKFB3 and PFKFB4 for future cancer therapy." (PMID 33671514, 2021). "However, recent evidence suggests that the FBPase-2 activity, specifically that of PFKFB4, may also be important for cancer cell survival." (PMID 24280138, 2013). "Our findings revealed significant differences in gene expression patterns for PFKFB4 and HMOX1 across various cancer types." (PMID 40739397, 2025). "This aligns with other studies suggesting that knocking down PFKFB4 and HMOX1 induces apoptosis and suppresses cancer cell growth." (PMID 40739397, 2025). "No previous studies have explicitly investigated the biological link between PFKFB4 and HMOX1 gene expressions using the GEPIA database, highlighting a gap in the current literature on their combined role in cancer survival outcomes." (PMID 40739397, 2025). "Gene expression analysis of PFKFB4 and HMOX1 was performed in all cancer cohorts of TCGA using the TIMER (Tumor Immune Estimation Resource) database." (PMID 40739397, 2025). "PFKFB4 has been found to activate the AKT pathway, which in turn promotes cell survival and proliferation in cancer cells." (PMID 39595571, 2024). "Both PFKFB4 and PKM2 are upregulated in different types of cancer and have been shown to promote the Warburg effect as well as glycolytic flux in cancer cells." (PMID 35697980, 2022). "Numerous other genes such as ESPL1, DOCK8, ARID3A, PFKFB4, ANKZF1, BANP and GRB7 showed elevated expression rates, some of which are known or suspected to be involved in cancer development and/or progression." (PMID 37193047, 2022). "This was reflected in the increased mRNA expression of the glycolytic enzymes PFKFB4 and PKM2, which are known to promote the Warburg effect and have been described as prognostic markers in different types of cancer." (PMID 35697980, 2022). "In many types of cancer, higher expression of PFKFB3 or PFKFB4 correlates with shorter overall survival (OS) or a more frequent presence of metastases." (PMID 33671514, 2021). "Therefore, PFKFB4 may be a potential target for the development of cancer therapeutics." (PMID 33803236, 2021). "In present study we found that PFKFB4 and SRC protein family was aberrantly overexpressed at mRNA level analyzed from the ENCORI Pan-Cancer Analysis Platform." (PMID 33593309, 2021). "The main focus is on the latest reports in this field of cancer research, and in particular the impact of PFKFB3 and PFKFB4 on tumor progression, metastasis, angiogenesis, and autophagy." (PMID 33671514, 2021). "PFKFB4, which has attracted more attention owing to its potential applications as a therapeutic target, is the major PFK2 isozyme in human cancers." (PMID 32487245, 2020). "Therefore, it is possible that DNMT3B and PFKFB4 interact through the PI3K/AKT pathway to regulate glycolytic activity and promote cancer progression." (PMID 39595571, 2024). "Moreover, cancer cell stemness markers OCT4 and SOX2 were detected quantitatively and high levels of SOX2 were found in PFKFB4‐OE MCF‐7 cells compared with normal MCF‐7 cells." (PMID 36127291, 2023). "Not surprisingly, PFKFB4-mediated glucose metabolism promoted cancer cell proliferation and maintenance of stemness of stem cells." (PMID 35590288, 2022). "Given the cancer specificity of PFKFB4, such compounds could open up a whole new avenue for inhibiting HIF-1α in a cancer specific manner." (PMID 36115843, 2022).
cancer (continued). "Thus, for neoplastic cells, both activities of cancer-specific PFK-II isoenzymes (PFKFB3, PFKFB4), although opposing, can significantly stimulate tumor progression." (PMID 34445551, 2021). "Therefore, not only the regulation of expression of cancer-specific PFKFB3 and PFKFB4 isoforms but also the regulation/modulation of the activity of two opposing domains will be crucial for the tumor progression." (PMID 34445551, 2021). "Independent studies have demonstrated that PFKFB4 is required for cancer cell survival but not for normal cell survival." (PMID 34211613, 2021). "The anti-cancer activity of sulforaphane is not mediated by direct inhibition of phosphofructokinase, but through the inhibition of the PFKFB4 pathway." (PMID 32756373, 2020). "PFKFB4 is one of the four isoforms of the bifunctional kinase and phosphatase enzyme PFK2 (6-phosphofructo-2-kinase/fructose-2,6-bisphosphatase) and plays a key role in glycolysis and gluconeogenesis in cancer." (PMID 31671779, 2019). "The present study investigated, by immunohistochemical analysis, the protein expression of HIF-1α, PDK1, PHD3, PFKFB4, and VEGFA, five genes extensively modulated in hypoxic conditions, the typical state of tumor microenvironment strictly connected with cancer cells growth and propagation." (PMID 29117193, 2017). "In metabolic screens PFKFB4 has been proposed as a new potential target in cancer therapy as its silencing increased the ROS level and inhibited survival of cancer cells but not epithelial cells." (PMID 27187453, 2016). "In addition, expression of 6-phosphofructo-2-kinase/fructose-2,6-biphosphatase 4 (PFKFB4), an isoform of PFK2, is elevated in tumors and an important regulator of cancer cell survival." (PMID 26576639, 2015). "We find that 5MPN is a selective inhibitor of PFKFB4 that suppresses the glycolysis and proliferation of multiple human cancer cell lines but not non-transformed epithelial cells in vitro." (PMID 26221874, 2015). "In addition, USP5 has been reported to stabilize glycolytic enzymes such as PFKFB4 and PFKP in cancer, raising the possibility that similar mechanisms may exist in RA." (PMID 41339332, 2025). "Considering that in cancers, PFKFB4 is critically involved in enhanced aerobic glycolysis, a phenomenon termed the Warburg effect, and we reckoned LINC01572 might exert its oncogenic effect via PFKFB4-enhanced glycolysis." (PMID 34970545, 2021). "Besides, it is also worthy to note the non-metabolic function of PFKFB4 that are relevant in cancer development." (PMID 31244553, 2019). "Without doubt, it is worth noting that PFKFB4 and PFKFB3 isoenzymes are not only involved in glucose metabolism but may also regulate other processes crucial for carcinogenesis, having a multi-level anti-cancer effect." (PMID 31754349, 2019).
tumor (71 papers, 2011 to 2025). "Activates tumor-associated macrophages which induce tumor cell death; Inhibition of the α-tubulin/PD-L1/PFKFB4 axis." (PMID 41246347, 2025). "The phosphofructo-2-kinase/fructose-2,6-biphosphatase 4 (PFKFB4) isozyme has been implicated in tumor development through its regulation of glycolytic and pentose phosphate pathway flux, as well as ATP synthesis in hypoxic cells." (PMID 39595571, 2024). "Our current study provided novel insights into the mechanisms underlying ER+ BC drug resistance and demonstrated that PFKFB4 plays an essential role during tumour cell stemness transformation and acquired CDK4/6 inhibitor resistance." (PMID 36127291, 2023). "Gene Pfkfb4, with 1.7 fold upregulation in WT tumor, encodes the tissue specific 6-phosphofructo-2-kinase/fructose-2,6-bisphosphatase 4 enzyme and is considered to be activator of the key regulatory enzyme of the glycolysis, fructose 2,6-bisphosphate (F2,6BP)." (PMID 34685767, 2021). "The upregulated expression of PFKFB4 was associated with high tumor grade (P=0.026) and advanced TNM stage (P=0.003)." (PMID 34093813, 2021). "Next, we studied the effects of PFKFB4 on cell proliferation and tumor growth and associated mechanisms in vitro and in vivo." (PMID 34211613, 2021). "We thus further studied clinicopathological associations of PFKFB4 and found its expression was associated with essential parameters like tumor stage, grade, nodal involvement or metastasis." (PMID 34593007, 2021). "High PFKFB4 expression assessed by IHC was associated with increased tumor stage and grade, and subsequent in vitro experiments demonstrated that PFKFB4 expression was induced during hypoxia in an HIF-1α-dependent manner." (PMID 33466735, 2021). "In a further IHC validation using 324 primary ccRCC sections, we found PFKFB4 expression significantly associated with older age, advanced tumor stage, grade and Ki-67 index." (PMID 34593007, 2021). "In breast cancer studies, coexpression of PFKFB3 and PFKFB4 was significantly associated with metastasis and chemotherapy resistance, suggesting that they may drive tumor progression through shared signalling pathways (such as the PI3K/AKT pathway)." (PMID 40438141, 2025). "Altogether, PFKFB4 caused metabolic reprogramming of tumour cells and enhanced glycolysis." (PMID 36127291, 2023). "High expression of PFKFB4 may be beneficial to inhibit the proliferation of tumor cells in the initial stage, thereby associated with better OS." (PMID 37770581, 2023). "Subsequently, a prognostic risk score for all tumor samples was calculated using the formula: prognostic risk score = expression level of G6PD*(0.15) + expression level of CENPA*(0.075) + expression level of STC2*(0.018) + expression level of PFKFB4*(0.053)." (PMID 35938165, 2022). "The upregulated expression of PFKFB4 was associated with high tumor grade and advanced TNM stage." (PMID 34093813, 2021). "In the present study, we identified five genes (LDHA, PPAT, BFSP1, NR0B1, and PFKFB4) associated with the tumour immune microenvironment in HCC patient cohorts that may be applied as potential biomarkers of HCC immunotherapy outcome." (PMID 33407546, 2021). "PFKFB4 overexpression was associated with advanced tumor grade, stage and worsened prognosis." (PMID 34593007, 2021). "Finally, the PFKFB4 gene encodes the isoforms predominantly found in the testis, although it has also been found in several types of tumor cells." (PMID 32717953, 2020). "Finally, the PFKFB4 gene encodes the isoenzyme occurring in the testis, although it has also been found in several types of tumor cells." (PMID 30234009, 2018). "In future studies, we will establish a cell-derived xenograft tumor model using LR HCC cells transfected with shPFKFB4 to validate the contribution of PFKFB4 to lenvatinib resistance in vivo." (PMID 40269756, 2025).